TMEM106A (transmembrane protein 106A)
Description:
Activates macrophages and polarizes them into M1-like macrophages through the activation of the MAPK and NF-kappaB signaling pathway. Upon activation, up-regulates the expression of CD80, CD86, CD69 and MHC II on macrophages, and induces the release of pro-inflammatory cytokines such as TNF, IL1B, IL6, CCL2 and nitric oxide (By similarity). May play a role in inhibition of proliferation and migration.
Synonyms: MGC20235
Tractability: Antibody: UniProt places it where antibodies can reach, with medium confidence; UniProt predicts a signal peptide or a membrane-spanning region; its Gene Ontology location is reachable by antibodies, with medium confidence. PROTAC: ubiquitination databases record sites on it.
Gene: Protein-coding gene on chromosome 17 (43,211,835 to 43,220,041, forward strand). Ensembl gene ENSG00000184988.
Subcellular location: Cell membrane
Gene Ontology:
Molecular function: protein binding
Biological process: intracellular signal transduction; macrophage activation
Cellular component: plasma membrane
Genetic constraint (gnomAD): Loss-of-function variants: 24 observed, 28.39 expected, observed/expected ratio (o/e) 0.85, 90% interval 0.61 to 1.19. The synonymous counts are far from expectation, so gnomAD's model fits this gene poorly and the ratio says little. Missense variants: 275 observed, 337.01 expected, observed/expected ratio (o/e) 0.82, 90% interval 0.74 to 0.9. Synonymous variants: 104 observed, 138.48 expected, observed/expected ratio (o/e) 0.75, 90% interval 0.64 to 0.88.
Homologues: Orthologues: chimpanzee TMEM106A (99% identical), macaque TMEM106A (95% identical), pig TMEM106A (81% identical), rabbit TMEM106A (78% identical), dog TMEM106A (73% identical), mouse Tmem106a (66% identical), rat Tmem106a (63% identical), guinea pig TMEM106A (54% identical).
Diseases named in the same sentence as TMEM106A in open-access papers:
TMEM106A is named in the same sentence as 29 diseases in open-access papers, as found by Europe PMC text mining. Sharing a sentence is not in itself a finding about the gene and the disease. The quoted sentences say what the papers report.
gastric cancer (8 papers, 2014 to 2025). A primary or metastatic malignant neoplasm involving the stomach. "TMEM106A, acts as a tumor suppressor and is regulated by promoter hypermethylation in gastric cancer cells, and FOSL1 has been linked to primary breast tumor metastasis." (PMID 32547604, 2020). "Loss or reduction of TMEM106A expression is associated with promoter region hypermethylation in gastric cancer (GC)." (PMID 26215746, 2015). "TMEM106A expression was found to be decreased in tumor tissue samples, and gastric cancer cell lines by hypermethylation of the promoter region." (PMID 37936608, 2023). "Similar to these results, TMEM106A methylation was detected in 88.6% of primary gastric cancer tissue samples and in 18.1% of normal gastric tissue samples, suggesting its potential diagnostic clinical value." (PMID 35713314, 2022). "Previous investigations indicated that human TMEM106A is a type II membrane protein, downregulated or silenced by promoter region hypermethylation in gastric cancer cell lines and primary gastric cancer tissues, but expressed in normal gastric tissues." (PMID 26215746, 2015). "Similarly, in gastric cancer, TMEM106A is frequently silenced by promoter hypermethylation; forced expression triggers apoptosis and slows tumor growth in vitro and in xenografts." (PMID 41354084, 2025). "This low expression was associated with increased cell proliferation and in contrast, induced overexpression of TMEM106A in gastric cancer cell lines is related to decreased cell proliferation and increased apoptosis due to the activation of the caspase cascade." (PMID 37936608, 2023). "TMEM106A plays an important role in immune and inflammation related diseases, mainly targeting viruses and cancer, including HIV, gastric cancer, and kidney cancer." (PMID 41459498, 2025). "TMEM106A was initially identified as a tumor suppressor gene, down-regulated in expression in gastric cancer (GC) cell lines but not in normal gastric tissues." (PMID 35359978, 2022).
hepatocellular carcinoma (3 papers, 2022 to 2025). A malignant tumor that arises from hepatocytes. "Hepatocellular carcinoma and renal cell cancer also show TMEM106A downregulation linked to tumor progression." (PMID 41354084, 2025). "Herein, we observed a decreased expression of TMEM106A in highly metastatic hepatoma cells, which was related to TMEM106A promoter methylation and was reversed by treatment with a demethylating agent, 5-Aza-2′-deoxycytidine." (PMID 35713314, 2022). "Herein, TMEM106A was demonstrated to have lower expression in highly metastatic hepatoma cells compared with that in poorly metastatic hepatoma cells." (PMID 35713314, 2022). "However, the role of TMEM106A in hepatocellular carcinoma (HCC) is still unknown." (PMID 35713314, 2022).
atherosclerosis (2 papers, 2025). A disease characterized by the build-up of fatty material and calcium deposition in the arterial wall resulting in partial or complete occlusion of the arterial lumen. "Given that atherosclerosis is a chronic inflammatory condition, and that atheroma plaques significantly contribute to ischemic stroke, we propose that TMEM106A plays a crucial role in the progression of ischemic stroke." (PMID 40371070, 2025). "By integrating machine learning with multi-omics bioinformatics, we established a novel three-gene signature (OAS2, TMEM106A, ABCB1) for precise diagnosis of atherosclerosis and ischemic stroke." (PMID 40371070, 2025). "While earlier works emphasized well-known inflammatory markers (e.g., IL6, TNF-α), we identified novel candidates (OAS2, TMEM106A, ABCB1) with limited prior links to atherosclerosis or stroke." (PMID 40371070, 2025).
glioblastoma (2 papers, 2014 to 2025). The most malignant astrocytic tumor (WHO grade IV). "To gain deeper insight into the spatial distribution of TMEM106A within the complex architecture of gliomas, we employed two complementary approaches: the publicly available Ivy Glioblastoma Atlas and a high‐resolution 10x Genomics Visium dataset." (PMID 41354084, 2025). "Conversely, its upregulation in COAD, ESCA, HNSC, LUAD, STAD, and glioblastoma (GBM) suggests TMEM106A's potential role in the aggressive biology of gliomas." (PMID 41354084, 2025).
glioma (2 papers, 2024 to 2025). A benign or malignant brain and spinal cord tumor that arises from glial cells (astrocytes, oligodendrocytes, ependymal cells). "The box plots reveal that TMEM106A is associated with tumor grade, particularly in the all‐glioma, IDHwt, and IDHmu groups." (PMID 41354084, 2025). "Taken together, TMEM106A serves as an independent prognostic factor and is associated with more aggressive glioma behavior, underscoring its potential prognostic utility, particularly in IDH‐wildtype astrocytomas (IDHwt)." (PMID 41354084, 2025). "The enrichment of these inflammatory pathways in TMEM106A‐high gliomas suggests that TMEM106A expression is tightly linked to an inflammatory tumor microenvironment, characterized by cytokine activity and macrophage‐driven signaling networks." (PMID 41354084, 2025). "Transmembrane protein 106A (TMEM106A), implicated as a tumor suppressor in various cancers, has an unclear role in gliomas." (PMID 41354084, 2025). "A summarized table categorizes each cancer type by direction (up‐ or down‐regulation) with a significance symbol; from this, TMEM106A appears to play a potential role in glioma." (PMID 41354084, 2025). "In this study, we present a comprehensive analysis of TMEM106A in gliomas, integrating multi‐omics with single‐cell sequencing and spatial transcriptome datasets using advanced bioinformatics and immunohistochemistry." (PMID 41354084, 2025). "Immunohistochemistry scores showed that TMEM106A is most highly expressed in high‐grade tumors, especially in IDH‐wildtype gliomas, whereas the intensity of TMEM106A staining in IDH‐mutant tumors remains comparatively subdued." (PMID 41354084, 2025). "For TMEM106A, the all‐glioma, IDHwt, and IDHmu groups demonstrated significant differences, whereas the Oligo group did not." (PMID 41354084, 2025). "Collectively, these data reveal that TMEM106A‐enriched gliomas exhibit a convergence of pro‐inflammatory and oncogenic signaling pathways, regardless of IDH mutation status." (PMID 41354084, 2025). "TMEM106A independently predicts survival and correlates with myeloid‐enriched transcriptional states in gliomas." (PMID 41354084, 2025). "In glioma, higher bulk TMEM106A expression correlates with higher grade and worse survival, yet single‐cell data indicate the transcript is most abundant in myeloid lineages." (PMID 41354084, 2025). "Collectively, TMEM106A reflects macrophage density, activation state, and spatial context, features that are jointly relevant to outcome in glioma." (PMID 41354084, 2025). "For TMEM106A, significant differences emerged in the all‐glioma, IDHwt, and Oligo groups, while the IDHmu did not." (PMID 41354084, 2025). "The identification of TMEM106A as an independent prognostic factor in glioma supports concrete clinical use cases." (PMID 41354084, 2025). "Across bulk transcriptomics (TCGA/CGGA), single‐cell, spatial, and IHC, we identify TMEM106A as an independent prognostic biomarker in glioma—most pronounced in IDH‐wildtype." (PMID 41354084, 2025). "TMEM106A's function might be co‐opted in gliomas to promote tumor aggressiveness, possibly through pathways that are dormant in other tissues of its microenvironment (i.e., immune cells) rather than directly impacting the tumor cells themselves." (PMID 41354084, 2025). "Through this multidisciplinary approach, we aim to determine whether TMEM106A can serve as a novel prognostic indicator and a potential candidate for glioma treatment strategies." (PMID 41354084, 2025). "Correlation between TMEM106A and 12 principal cell compartments in glioma subtypes." (PMID 41354084, 2025). "Correlation of TMEM106A expression with 22 immune cell types across glioma subtypes." (PMID 41354084, 2025).
glioma (continued). "Across modalities, signals converge on a microenvironmental interpretation of TMEM106A in glioma." (PMID 41354084, 2025). "This is particularly useful in IDH‐wildtype lower‐grade gliomas, where TMEM106A‐high status may flag tumors with GBM‐like behavior." (PMID 41354084, 2025). "To further elucidate the functional impact of TMEM106A overexpression in gliomas, we performed gene set enrichment analysis (GSEA) across three principal molecular subtypes: IDH‐wildtype astrocytomas (IDHwt), IDH‐mutant astrocytomas (IDHmu), and oligodendrogliomas (Oligo)." (PMID 41354084, 2025). "To comprehensively evaluate TMEM106A's role in glioma, we began by examining all its relatives from the entire TMEM106 family (including TMEM106A, TMEM106B, and TMEM106C) within the context of glioma." (PMID 41354084, 2025). "From the initial bioinformatics characterization, both TMEM106A and its paralog TMEM106C initially appeared significant in differential expression and survival analyses of glioma." (PMID 41354084, 2025). "The parsimonious interpretation is therefore microenvironmental: bulk TMEM106A levels likely reflect myeloid infiltration rather than a glioma‐cell–intrinsic oncogenic role." (PMID 41354084, 2025). "This study is observational and was not designed to demonstrate a glioma‐cell–intrinsic function for TMEM106A." (PMID 41354084, 2025). "TMEM106A is an intriguing candidate biomarker that has not been studied in gliomas to date." (PMID 41354084, 2025).
lung carcinoma (2 papers, 2022 to 2025). "For instance, lung cancer cells exhibit silencing of TMEM106A, and restoring TMEM106A in non‐small cell lung cancer (NSCLC) suppresses proliferation, invasion and induces apoptosis." (PMID 41354084, 2025). "The downregulation of LINC01537 and TMEM106A was observed in lung cancer development, which was involved in tumor metabolic reprogramming or EMT." (PMID 35433477, 2022).
renal cell carcinoma (2 papers, 2023 to 2025). "In renal cell carcinoma (RCC), reduced levels of mRNA and TMEM106A protein were reported in five cell lines RCC 786-O, 769-O, ACHN, A498, and A794 compared with the control cell lines of renal proximal tubular epithelium and primary renal cortical epithelium." (PMID 37936608, 2023).
AIDS (1 paper, 2025). A syndrome resulting from the acquired deficiency of cellular immunity caused by the human immunodeficiency virus (HIV). "Although, TMEM106A plays a role in various immune diseases, such as AIDS and cancer." (PMID 41459498, 2025).
astrocytomas (1 paper, 2025). "In IDH‐wildtype astrocytoma, TMEM106A‐high exhibited significantly higher IPS when PD‐1 was “on”: ips_ctla4_neg_pd1_pos (p = 0.037) and ips_ctla4_pos_pd1_pos (p = 0.021)." (PMID 41354084, 2025). "In IDH‐mutant astrocytoma, IPS differences were attenuated: PD‐1–positive comparisons trended higher in TMEM106A‐high (ctla4_neg/pd1_pos and ctla4_pos/pd1_pos, p ≈ 0.09), whereas PD‐1–negative contrasts were null (both p = 0.57)." (PMID 41354084, 2025).
breast carcinoma (1 paper, 2022). "Previous studies have reported the downregulation of TMEM106A expression during tumorigenesis of lung and breast cancers." (PMID 35713314, 2022).
gastric tumour (1 paper, 2014). "We then studied the tumour suppressive effect of TMEM106A against gastric tumour formation in vivo: tumour growth was significantly inhibited in nude mice inoculated with HGC-27/Ad5-TMEM106A compared with those inoculated with HGC-27/Ad5-Null." (PMID 24975047, 2014).
idiopathic pulmonary fibrosis (1 paper, 2024). Idiopathic pulmonary fibrosis (IPF) is a nonneoplastic pulmonary disease that is characterized by the formation of scar tissue within the lungs in the absence of any known cause. "In addition, they performed mediation analysis and confirmed that some proteins, PARP1, GDI2, and TMEM106A, exerted indirect effects on some diseases, such as prostate cancer, uterine leiomyoma, and idiopathic pulmonary fibrosis through telomere length." (PMID 38431573, 2024).
ischemic stroke (1 paper, 2025). A stroke disorder caused by obstruction of blood flow to the brain, due to thrombotic (local blood clot formation) or embolic (due to a blood clot or other material traveling from another site) event. "Comprehensive bioinformatics analysis identified three hub genes—OAS2, TMEM106A, and ABCB1—with high prognostic value for ischemic stroke." (PMID 40371070, 2025). "Furthermore, we established a gene panel that includes OAS2, TMEM106A, and ABCB1 to evaluate their potential in predicting the diagnosis of atherosclerotic plaques and ischemic stroke." (PMID 40371070, 2025). "Furthermore, our results indicate that OAS2, TMEM106A, and ABCB1 may serve as promising candidates for the diagnosis and assessment of atherosclerotic plaques and ischemic stroke." (PMID 40371070, 2025).
serous ovarian carcinoma (1 paper, 2021). "In an Italian woman diagnosed with high-grade serous ovarian carcinoma, the deletion of a 137.8-kb region, encompassing the first six exons of the BRCA1 gene and the full length of NBR2, BRCA1P1, NBR1, and transmembrane protein 106A (TMEM106a) genes, was detected." (PMID 34926299, 2021).
urothelial bladder cancer (1 paper, 2025). "By integrating WGBS data with The Cancer Genome Atlas (TCGA) urothelial bladder cancer dataset, Transmembrane Protein 106A (TMEM106A) was identified as a novel UC biomarker." (PMID 40282460, 2025).
viral infection (1 paper, 2022). "Our mapping assays showed that the extracellular region of TMEM106A anchored on the plasma membrane is sufficient to inhibit virus infection." (PMID 35359978, 2022). "Combined approaches measuring viral infection, gene expression, and protein interactions uncovered that TMEM106A is required for optimal IFN-mediated viral inhibition and interferes with EV-A71 binding to host cells on the receptor scavenger receptor class B member 2 (SCARB2)." (PMID 35359978, 2022). "TMEM106A specifically blocks SCARB2-mediated viral infection." (PMID 35359978, 2022). "Thus, our data indicated that TMEM106A blocks SCARB2-dependent viral infection." (PMID 35359978, 2022).